FOXP3 (forkhead box P3)
Diseases named in the same sentence as FOXP3 in open-access papers (continued):
Sharing a sentence is not in itself a finding about the gene and the disease.
cancer (continued). "Similarly, higher SET and CIP2A levels in human CRC cancers are positively correlated with CD8+ cytotoxic T infiltration but negatively correlated with Foxp3+ Treg infiltration." (PMID 34911954, 2021). "Similarly, several studies have shown the importance of the ratio between CD4+ /, CD8+ / or CD3+ and FOXP3+ cells as being crucial in predicting prognosis of cancer patients." (PMID 34493268, 2021). "Furthermore, aspirin reduced Foxp3+ regulatory T cells and prolonged survival in a mouse model and showed effects on Cox-2 expressed in cancer cells, which is involved in carcinogenic pathways (i.e. RAS and NF-κB)." (PMID 33618686, 2021). "Moreover, transient FOXP3-expressing Treg depletion in combination with systemic administration of anti-PD-1 Ab successfully induced severe hepatic irAEs in orthotopic cancer mice." (PMID 33665689, 2021). "We speculated that the disruption of such a protein complex by using synthetic peptides able to bind Foxp3 might have an impact on the functionality of Treg cells and thus have a therapeutic potential in cancer treatment." (PMID 33671179, 2021). "FOXP3 is considered to be the most reliable Treg lymphocyte marker in human cancer." (PMID 33726701, 2021). "Finally, the involvement of SOCS1, TAB2, and Foxp3 as direct targets for TNF-α gene in both cancer types was assessed." (PMID 34900737, 2021). "One of these subsets, CAF-S1, has been associated with the accumulation of FOXP3+ T lymphocytes and CD4+CD25+ T lymphocytes in the tumor, both populations related with cancer cell stemness as explained in the next section, while CAF-S4 has been associated with an increase of stromal cells." (PMID 33530455, 2021). "Meanwhile, lower protein expression of SOCS1 and Foxp3 was only evident in both cachectic cancer groups without any association between TAB2 protein expression and the presence of cachexia." (PMID 34900737, 2021). "In addition to the presence in lymphocytes, there are increasing publications showing the expression of FOXP3 in the cancer cells, suggested that FOXP3 has a broader role than initial thoughts." (PMID 33116119, 2020). "As well, the BMI>35 cohort had a significantly (P = 0.014) lower proportion of natural killer (NK) cells (i.e., for CD56 bright cells and a trend for CD56 dim cells) and a trend towards higher Tregs (CD4+CD127low/-CD25+FoxP3+ cells), suggesting a potentially poorer ability to eradicate cancer cells." (PMID 32027700, 2020). "The present data do not identify any single precipitating factor for SIR in CRC but indicate that infiltration of FOXP3+ T-regulatory cells may have an effect on cancer-specific survival." (PMID 32316975, 2020). "To date, the role of Foxp3 regulator T cells in cancer is still conflicting." (PMID 32758195, 2020). "The population of these cells in cancer outnumbers the cells with a CD4+CD25+Foxp3+ phenotype, they have the ability to release immunosuppressants such as IL10 and TGF-β1, and the number of these cells increases progressively in HCC along with the stage of the disease." (PMID 32488850, 2020). "However, the results of these studies indicated that the role of FOXP3 in cancers was controversial." (PMID 33116119, 2020). "FOXP3, a surface marker of regulatory T cell (Treg), could promote cancer cells to escape immune surveillance." (PMID 33154945, 2020). "Therefore, numerous investigations are being carried out to identify potential targets such as galectin-1, cancer associated cathepsins, OX40+Foxp3+ Treg cells, etc., to develop new therapies and to achieve greater treatment efficacy." (PMID 32645977, 2020). "We provided the rationale that cancer-FOXP3 could identify PDAC patients suited for combination of ICI and the chemokines/chemokine receptors inhibitor, in order to improve response." (PMID 32782241, 2020).
cancer (continued). "Discovering new treatment modalities against FOXP3 is very promising because it can decrease the suppression of immune function, and may improve patients with cancers that are resistant to radioiodine therapy." (PMID 32606302, 2020). "In spite of the significantly prognostic differences in the subgroups of Gal-9 on TILs in combination with PD-L1 on cancer cells (p=0.046) or FOXP3 (p=0.014), the double immune biomarkers positive group failed to fully reflect the objective fact for its limited sample size." (PMID 33082168, 2020). "Indeed, co-culture of Foxp3+ IL-17+ T cells with colorectal cancer cells increased the number of cancer cell colonies." (PMID 32121394, 2020). "However, the prognostic value of FoxP3+ T-cells differs considerably with respect to different types of cancer." (PMID 32785290, 2020). "Furthermore, tumoral PD-L1(+)/FOXP3+/low TILs were associated with worse clinical outcomes in EBV-positive and MSI-high carcinomas." (PMID 32498695, 2020). "Also, to investigate “Sor-Tau” combination effect on FOXP3 gene expression and its intracellular staining by flowcytometry in cancer cells as well as PBMCs as normal control cells." (PMID 31653148, 2019). "Overall, NFAT1 closely interacts with FOXP1 or FOXP3 in cancer progression." (PMID 31815635, 2019). "Of note, the prognostic value of FoxP3+ Tregs in cancer is controversial." (PMID 30926808, 2019). "Indeed, the induction of Foxp3 expression by a subset of cancers in the clinic has also been shown to promote metastasis through increased proliferation, migration, and invasion." (PMID 31690033, 2019). "Since alteration of the human immune system can contribute to the development of human cancer, FOXP3 has attracted attention in recent decades as one of the main transcription factors for Tregs, an important participant of immune evasion and surveillance in TME." (PMID 30782783, 2019). "Interestingly, qPCR revealed that there was a negative correlation between Syndecan-1 and each of IL-4, IL-17, and Foxp3 mRNA expression in carcinoma tissues of IBC and that the correlation was reversed in non-IBC." (PMID 31145753, 2019). "Several carcinomas and cancer cell lines produce IL‐10 and FoxP3, indicating that tumors may promote a biased Th2 response promoting IgG4, but limiting immune responses and enabling the escape from immune clearance." (PMID 29164823, 2018). "Although FOXP3 has been widely studied in immune system and cancer development, its function in the regulation of the UBC9 gene (for the sole E2 enzyme of SUMOylation) is unknown." (PMID 30011797, 2018). "Persistent Foxp3 expressors highly expressed the coinhibitory/costimulatory molecules Ctla4, Icos and Tigit, and the serine protease Gzmb, all of which are involved in cancer immunity." (PMID 29991564, 2018). "The prognostic value of Foxp3+ Tregs in cancer remains controversial." (PMID 30285868, 2018). "Complicating the issue of Tregs in cancer progression, a recent meta-analysis revealed that increased frequencies of Foxp3+ Tregs correlated with decreased overall survival in several cancers, but correlated with a better prognosis in head and neck, esophageal, and colorectal cancers." (PMID 29623082, 2018). "In another study, FOXP3+ Treg cells expressed in a heterogeneous population of cells that have both regulatory and non-regulatory T-cell functions induce the secretion of heterogeneous cytokines, which play a variety of roles in cancer progression." (PMID 30285668, 2018). "Thus, the further understanding of Treg induction and regulation of FOXP3 expression is highly relevant to expand the therapeutic opportunities for autoimmune and inflammatory diseases as well as cancer." (PMID 29730990, 2018). "More importantly, these FOXP3-bound genes are involved in the development and metastasis of cancer." (PMID 29549328, 2018). "Several studies also suggested that FoxP3 is expressed in B cells, macrophages and cancer cells." (PMID 30083152, 2018).
cancer (continued). "FOXP3+ T cells are common regulators of cytotoxic T-cell responses, and high levels of peripheral CD4+CD25+FOXP3+ regulatory T cells have been associated with poor clinical response to adoptive cell therapy in human cancer." (PMID 29930558, 2018). "In addition to Tregs, the expression of FOXP3 is reported in various cancer cell lines including Jurkat, a T-ALL cell line." (PMID 30103821, 2018). "The role of cancer cell FOXP3 in tumorigenesis is conflicting." (PMID 28716029, 2017). "Our data also suggest that IL-21 could be beneficial as a therapeutic agent across a variety of cancers, due to its ability to inhibit FOXP3 induction across all the cancer cell lines tested." (PMID 28239749, 2017). "As TGFβ1 has been shown to induce FOXP3 expression in naïve T cells, we next determined whether our cancer cell lines expressed TGFβ1 by flow cytometry." (PMID 28239749, 2017). "Forced expression of FOXP3 significantly decreased the self-renewal ability of cancer stem cells." (PMID 28591725, 2017). "Abundant expression of FOXP3 have been identified in different cancers." (PMID 28591725, 2017). "Similarly to TGFβ blockade, IL-21 was able to potently inhibit baseline FOXP3 induction in naïve T cells and FOXP3 induction as a result of the addition of cancer cell supernatants." (PMID 28239749, 2017). "We have recently shown that Helios is a marker of activated Tregs expressing immunosuppressive molecules GARP/latency-associated peptide (LAP) and that co-expression of Helios and FoxP3 with GARP/LAP can be used to identify expanded Treg subset in cancer patients." (PMID 28603527, 2017). "FOXP3 has constantly been regarded as a transcriptional factor functioned in cancer cells." (PMID 28716029, 2017). "The augmentation of Foxp3 positive lymphocytes in the fields adjacent to cancer cells was observed." (PMID 28831395, 2017). "Although increased FOXP3 activation has been revealed in many cancer types, its role in CSCs is largely unknown." (PMID 28591725, 2017). "The function of CD4+CD25+Foxp3+Tregs in cancer had been described as highly variable." (PMID 28529951, 2017). "We detected expression of Foxp3 also in some nuclei of cancer cells." (PMID 28831395, 2017). "In contrast, addition of cancer cell supernatants further increased FOXP3 expression in naïve T cells, and this increased expression correlated not only with T cell inhibition in the same cultures, but in subsequent cultures with freshly isolated naïve T cells." (PMID 28239749, 2017). "Thus, this study demonstrated, for the first time, an association between FOXP3 and CXCL12 genetic polymorphisms with this cancer, demonstrating that these markers are, somehow, involved in WT pathogenesis." (PMID 27830498, 2016). "This classification has been used to analyze FOXP3+ T cells in autoimmune diseases and cancers." (PMID 26864030, 2016). "This indicates that SMYD3 might be involved in cancer through suppression of cancer immunity and dampen anti-tumor immune response via promoting Foxp3-dependent immune suppressive pathways." (PMID 27790639, 2016). "Indeed, previous studies demonstrated that, in contrast to a wide range of human cancers, CRC infiltration by FOXP3+ regulatory T cells, is associated with an improved prognosis." (PMID 27552968, 2016). "Taken together, these results may indicate a role for this marker in cancer progression, raising new possibilities for research, targeting FOXP3." (PMID 27830498, 2016). "FOXP3 transcription factor has different expression patterns in a great variety of cell types, and its role in cancer remains unclear." (PMID 27830498, 2016). "Moreover, Foxp3+TILs, as a group of suppressive T cells, have been extensively studied in cancers and some clinical studies indicating that increased Foxp3+TILs levels are negative prognostic factors." (PMID 27602763, 2016).
cancer (continued). "Using this system, we screened our chemical library consisting of approximately 2,100 compounds and discovered that a cancer chemotherapeutic drug epirubicin restored the Foxp3-inhibited NF-κB activity in a concentration-dependent manner without influencing cell viability." (PMID 27284967, 2016). "Interestingly, FoxP3+ Tregs have been shown to be stably maintained or increased in the peripheral blood or TILs of cancer patients treated with ipilimumab or tremelimumab." (PMID 27509527, 2016). "Moreover, in addition to Treg cells, Foxp3 is found to be expressed in various other cells, such as many different types of cancer cells and epithelial cells from mammary glands, lung bronchia and prostate glands." (PMID 27965581, 2016). "Collectively, p300 is critical for the homeostasis and function of Foxp3+ Treg cells, and targeting p300 could be a new approach for cancer immunotherapy." (PMID 26075180, 2015). "The overall pooled analysis of all types of cancer found a negative prognostic effect associated with FoxP3+ Tregs preponderance." (PMID 26462617, 2015). "The prognostic value of FoxP3+ regulatory T cells (Tregs) in cancer remains controversial." (PMID 26462617, 2015). "In particular, it is unknown whether Foxp3 regulates transcription in cancer cells as it does in Tregs." (PMID 25779374, 2015). "Therefore, we conducted a systematic review and meta-analysis, aiming to establish pooled estimates for survival outcomes based on the presence of intratumoral FoxP3+ Tregs infiltrating in different types of cancer." (PMID 26462617, 2015). "Thus, the role of Foxp3 expression in cancer cells (referred as ‘cancer cell-derived Foxp3’ in this report) remains incompletely understood, especially regarding molecular mechanisms." (PMID 25779374, 2015). "Since FOXP3 can functionally interact with NF-κB to induce transcriptional activity of miR-146a, the FOXP3-miR-146-NF-κB axis could be a potential therapeutic target for cancers with FOXP3 defects." (PMID 26682271, 2015). "We identified direct and indirect target genes of cancer cell-derived Foxp3 for the first time." (PMID 25779374, 2015). "Therefore, cancer cell-derived Foxp3 appears to regulate gene transcription through multiple patterns, such as direct regulation, regulation of other transcriptional factors, and regulation of proteins that bind to other transcriptional factors." (PMID 25779374, 2015). "Further studies such as dual-luciferase reporter gene assay and microenvironment co-cultured model could be used to confirm the mechanism of regulating specific genes by cancer cell-derived Foxp3." (PMID 25779374, 2015). "Together, p300 is critical for the function and homeostasis of Foxp3(+) Treg cells, and thus p300 inhibitors are able to impair the function of Treg cells without affecting T effector cells suggesting a new approach for cancer immunotherapy." (PMID 26075180, 2015). "Foxp3+CD4+ T cells may benefit the host by modulating inflammation, which is linked to the angiogenesis of cancer." (PMID 26604855, 2015). "The results confirmed that cancer cell-derived Foxp3 affected gene expression in TSCC cells." (PMID 25779374, 2015). "This is the first report presenting the DNA binding profile of cancer cell-derived Foxp3." (PMID 25779374, 2015). "We initially speculated that cancer cell-derived Foxp3 may directly regulate the transcription of some extracellular factors, such as cytokines and chemokines, similarly to Foxp3 in Tregs." (PMID 25779374, 2015). "Forkhead box protein 3 (Foxp3), primarily identified as a transcription factor for Treg, is likely to be responsible for its immunosuppressive function and has popularly become its single marker in cancer research." (PMID 24276989, 2014).
cancer (continued). "Although Foxp3 is a master transcription factor for Treg cells, Foxp3 and IL-10 are expressed in several carcinoma tissues and cultured cancer cell lines, suggesting that cancer cells induce the Treg cell-like immunoregulatory milieu to evade immunosurveillance." (PMID 25132998, 2014). "While a large number of markers for Tregs have been proposed, FOXP3 remains the single most widely applied phenotypic credential of regulatory activity in cancer and other studies, despite being transiently expressed in activated human and canine conventional T cells lacking regulatory function." (PMID 25119018, 2014). "It is already becoming clear that cancer cells can show dysregulated FOXP3 expression." (PMID 24591761, 2014). "To examine whether the expression of the immunosuppressive cytokines IL-10 and TGF-β corresponded with the Foxp3+ expressing cancer cells we stratified in two different groups according to the percentages of expression in the immunohistochemical analysis." (PMID 23382847, 2013). "FOXP3 lacks some exons in MCF-7 cells; thereby these variants could lose the ability to suppress gene expression involved in cancer malignancy." (PMID 24155921, 2013). "The immunoregulatory function of FOXP3 may hinder the induction of immune responses against cancer and infectious agents, and thus, development of inhibitors of its functions might give new therapeutic opportunities for these diseases." (PMID 24350059, 2013). "FOXP3 is an accurate marker of primary Tregs in patients with immune-related disease and cancer." (PMID 23759077, 2013). "Foxp3 expression in cancer cells may have a number of functions related to the evasion of the immune response, including the modulation of cytokines, chemokines, hormones and other proteins related to invasion and metastasis, but this remains to be examined." (PMID 24179494, 2013). "Whether the Foxp3+ cells widely described in many cancer settings are of natural or adaptive/induced type remains largely a bone of contention." (PMID 23874336, 2013). "Further clarification of FOXP3-functions may facilitate the development of novel therapeutic approaches targeting LCK-FOXP3 pathway to suppress cancer malignancy for personalized and selective targeted medicine." (PMID 24155921, 2013). "Overall, the prognostic value of FOXP3+ Treg in cancer is questionable, although it is possible that the introduction of more specific assays for Treg might provide a more discriminating approach for evaluating their prognostic value." (PMID 23730621, 2013). "Serial morphological analysis demonstrated Foxp3 to be expressed in cancer cells." (PMID 23382847, 2013). "Based on this, developing molecular target therapy against CCR7 and FOXP3 might be a promising strategy for cancer treatment." (PMID 24040244, 2013). "However the percentages of Foxp3+ Treg cells in the cervical CIN group were slightly higher than the UCC group, indicating that with the progression of cancer, percentages of Foxp3+ Treg cells gradually increased." (PMID 23587428, 2013). "CD8+Foxp3+ T cells were reported to mediate immunosuppression in cancer patients." (PMID 22890822, 2013). "Viewing FOXP3 as a multifaceted factor of cancer biology may provide another explanation for its bifacial prognostic value." (PMID 24649219, 2013). "To examine whether Foxp3+ Treg expression corresponded with the Foxp3+ cancer cell expression, we stratified two different groups according to percentages expression of immunohistochemical analysis." (PMID 23382847, 2013). "We consider that further clarification of transcriptional mechanism of FOXP3 may facilitate the development of novel therapeutic approaches to suppress cancer malignancy." (PMID 24155921, 2013). "Interestingly, an inverse correlation between the number of Foxp3+ Treg and the level of Foxp3+ cancer cells was observed in our patients with CRC suggesting an anti-proliferative effect of TGF-β on Treg." (PMID 23382847, 2013).